SLC31A1 (solute carrier family 31 member 1)
Diseases named in the same sentence as SLC31A1 in open-access papers (continued):
Sharing a sentence is not in itself a finding about the gene and the disease.
breast cancer (continued). "High SLC31A1 expression correlated with a poor prognosis in patients with breast cancer, compared with low SLC31A1 expression." (PMID 35996075, 2022). "According to the median cut-off value, 517 patients with breast cancer were divided into high and low SLC31A1 expression groups, respectively." (PMID 35996075, 2022). "SLC31A1 exhibits a promising therapeutic target for cuproptosis-induction and combined therapy in breast cancer." (PMID 35996075, 2022). "To conclude, we investigated the prognostic and biological role of cuproptosis-related gene SLC31A1 in breast cancer." (PMID 35996075, 2022). "We tested whether tumor SLC31A1 expression and systemic copper dynamics reflect a coordinated tumor systemic copper axis in breast cancer (BC)." (PMID 42268797, 2026). "In addition, SLC31A1 promotes the development of breast cancer by activating the PI3K‐PDK1‐AKT signaling pathway and the EMT (Epithelial–mesenchymal transition) gene‐phenotype." (PMID 39676279, 2024). "SLC31A1 has great potential to regulate immunotherapy and chemotherapy resistance in breast cancer." (PMID 39676279, 2024). "It was also shown that SLC31A1 was correlated with the histological subtype of breast cancer, as patients with aggressive TNBC and human epidermal growth factor-2 (HER2+) cancer subtypes had higher SLC31A1 expression than patients with luminal A and B cancer subtypes." (PMID 38732186, 2024). "Pomegranate juice anthocyanidins may induce DNA damage and death of human breast cancer cells MDA‐MB‐231 by up‐regulating SLC31A1 to mobilize intracellular copper ions and ROS production." (PMID 39676279, 2024). "It was found that the G2E3‐AS1/let‐7a‐5p and CDKN2B‐AS1/let‐7b‐5p pathways may act as upstream lncRNAs and miRNAs of SLC31A1 to up‐regulate the SLC31A1 expression in breast cancer." (PMID 39676279, 2024). "Moreover, elevated SLC31A1 expression in breast cancer samples indicates poor prognosis, shorter overall survival, and a dysregulated immune response." (PMID 39867656, 2024). "Notably, high expression of SLC31A1 enhances breast cancer’s sensitivity to porphyrosol, thereby improving its therapeutic effect." (PMID 39702350, 2024). "SLC31A1 was significantly increased in breast cancer samples than those in normal tissues." (PMID 37884650, 2023). "Furthermore, we found that the expression level of SLC31A1 in the tumor tissue of all breast cancer subtypes was higher than that in the normal tissue through the UALCAN website." (PMID 37275369, 2023). "In addition, we explored the correlation between SLC31A1 and immune markers of various tumor immune infiltration cells in breast cancer." (PMID 37275369, 2023). "Gene expression of SLC31A1 in breast cancer samples and adjacent normal tissues were analyzed." (PMID 37884650, 2023). "This study might provide important information to uncover the role of cuproptosis-related gene SLC31A1 in breast cancer and might offer a new strategy to treat breast cancer through intervening the LINC01614/miR-204-5p/SLC31A1 axis." (PMID 37884650, 2023). "Furthermore, we analyzed the differential expression of 24 immune cells between the high SLC31A1 expression group and the low SLC31A1 expression group in breast cancer." (PMID 37275369, 2023). "In summary, this study found that SLC31A1 was a potential cuproptosis-related gene, which was significantly upregulated and was able to predict diagnosis, prognosis, chemosensitivity, and immune infiltration in breast cancer." (PMID 37884650, 2023). "It is reported that overexpressing SLC31A1 could increase copper uptake in breast cancer cells and xenograft models and could also promote cuproptosis in kidney and lung cancer cell lines." (PMID 36902801, 2023). "The LINC00511/miR-29c-3p/SLC31A1 axis may promote invasion and metastasis in breast cancer through the regulation of copper transport." (PMID 37275369, 2023).
breast cancer (continued). "Taken together, these findings suggest that SLC31A1 might be the most potential cuproptosis-related gene and could be a promising unfavorable prognostic biomarker in breast cancer." (PMID 37884650, 2023). "Furthermore, we found that SLC31A1 was highly expressed in many immune cells in breast cancer, including aDC, DC, iDC, macrophage, neutrophil, T helper cells, Tcm, Tgd, Th1, and Th2." (PMID 37275369, 2023). "Moreover, we found that the expression of SLC31A1 was positively correlated with CAF in luminal A breast cancer." (PMID 37275369, 2023). "Our study attempted to investigate whether the expression of SLC31A1 is related to the level of immune infiltration in breast cancer through the TIMER website." (PMID 37275369, 2023). "Thus, there is a major need to evaluate SLC31A1 expression in different molecular subtypes of breast cancer treated with different chemotherapy regimens." (PMID 37884650, 2023). "Moreover, SLC31A1 was significantly positively correlated with different immune cells infiltration, immune cell biomarkers, and immune checkpoints in breast cancer." (PMID 37884650, 2023). "Expression level of SLC31A1 was increased in breast cancer samples with respect to normal tissues." (PMID 37884650, 2023). "Furthermore, the expression level of SLC31A1 in breast cancer was positively correlated with tumor immune cell infiltration, immune cell biomarkers and cancer-associated fibroblast (CAF)." (PMID 37275369, 2023). "Combined with our correlation analysis, YTHDF3 may upregulate the expression of SLC31A1 by increasing its m6A methylation, promoting the metastasis of breast cancer cells." (PMID 37275369, 2023). "Importantly, the LINC00511/miR-29c-3p/SLC31A1 axis was identified as the most potential pathway promoting breast cancer progress by affecting copper transport." (PMID 37275369, 2023). "In summary, SLC31A1 mRNA is upregulated in breast cancer and correlated with unfavorable prognosis." (PMID 37275369, 2023). "Collectively, LINC01614/miR-204-5p/SLC31A1 might be a potential axis related to cuproptosis in breast cancer." (PMID 37884650, 2023). "LINC01640/miR-204-5p/SLC31A1 might be a significant and promising axis during cuproptosis in breast cancer." (PMID 37884650, 2023). "Therefore, SLC31A1 upregulation and intracellular copper accumulation represent a possible mechanism for breast cancer tumorigenesis and progression." (PMID 35996075, 2022). "In addition to breast cancer, higher levels of SLC31A1 were found in tumor samples of bladder, cervical, esophageal, uterine, stomach, head and neck cancers, as well as pheochromocytoma and paraganglioma, compared with normal samples." (PMID 35996075, 2022). "In addition, GSEA revealed that cellular functions associated with metabolism and cardiomyopathy were enriched in breast cancer patients with low SLC31A1 expression." (PMID 35996075, 2022). "Hence, it is plausible that SLC31A1 overexpression induces copper homeostasis dysregulation, thus possibly interfering with antitumor immune effects in breast cancer." (PMID 35996075, 2022). "The LINC01614/miR-204-5p/SLC31A1 axis may play a major role in cuproptosis-related breast cancer." (PMID 39325172, 2024). "SLC31A1 expression is increased in cervical cancer, endometrial cancer (EC) and breast cancer (BC), but decreased in clear cell renal cell carcinoma (ccRCC), hepatocellular carcinoma (HCC) and lung adenocarcinoma (LUAD)." (PMID 39482784, 2024). "Consequently, SLC31A1 presents an intriguing target for breast cancer treatment strategies." (PMID 39702350, 2024). "However, the expression level and function of SLC31A1 in breast cancer are still unclear." (PMID 37275369, 2023). "Studies have shown that breast cancer patients with poor prognoses exhibit higher expression of the copper importer solute carrier family 31 member 1 (SLC31A1) and the copper binding protein ceruloplasmin, which could be utilized as potential prognosis factors." (PMID 37180167, 2023).
breast cancer (continued). "SLC31A1 can be regulated by AMPK signal and can also regulate AKT signal and EMT gene‐phenotype to promote the growth of breast cancer." (PMID 39676279, 2024). "Consistent with the data from R language, starBase showed that expression levels of CDKN2A, SLC31A1, ATP7B, and PDHB were markedly up-regulated in breast cancer with respect to normal samples." (PMID 37884650, 2023). "However, as a copper death-related gene, the mechanism of SLC31A1 in breast cancer remains unclear." (PMID 37275369, 2023). "The expression of ATP7B and SLC31A1 were decreased and increased, respectively, in the basal-like subtype patients, suggesting that patients with the basal-like subtype of breast cancer may have different levels of copper in their tumor tissues compared with those with other breast cancer subtypes." (PMID 37180167, 2023). "Prognostic values of two cuproptosis-related genes in breast cancer, namely CDKN2A and SLC31A1, were then evaluated." (PMID 37884650, 2023). "However, the mechanism of SLC31A1 in breast cancer remains unclear." (PMID 37275369, 2023). "We found that genes DLAT, SLC31A1, ATP7A and ATP7B were significantly related to the overall survival (OS) of breast cancer patients in univariate Cox regression analysis." (PMID 35996075, 2022). "Since DLAT, SLC31A1, ATP7A and ATP7B were all found to be related to prognosis in breast cancer, a combined prognostic model aggregating more cuproptosis-related genes and clinical features is expected in future." (PMID 35996075, 2022). "This is also supported by the increased expression of SLC31A1, SCO1, and COX11 mRNA observed in cell lines with a different tissue origin, such as MCF7 (breast cancer) and PC3 (prostate cancer)." (PMID 27516958, 2016). "In an experiment targeting human breast cancer cells MCF‐7, SLC31A1 silencing significantly eliminated CoCl2‐induced E‐cadherin downregulation and vimentin up‐regulation, which inhibited tumor progression by inhibiting CoCl2‐induced cytoskeleton rearrangement and EMT marker genes expression." (PMID 39676279, 2024). "Recently, high SLC31A1 expression in breast cancer patients has led to poor overall survival, distant metastasis-free survival, and relapse-free survival (RFS), suggesting that SLC31A1 may be an unfavorable prognostic biomarker." (PMID 39867656, 2024). "In particular, no statistical prognostic value of CDKN2A in breast cancer was observed, while patients with higher expression of SLC31A1 displayed a poor prognosis." (PMID 37884650, 2023). "Up-regulation of SLC31A1 expression and regulation of copper ion transport mediated by LINC00511-miR-29-3p axis is related to poor prognosis and positively correlated with tumor immune infiltration in breast cancer." (PMID 37275369, 2023). "Additionally, it was discovered via research of the impact of gene expression patterns on overall survival in breast cancer that those expressing high levels of ATP7A, DBT, DLAT, DLD, GLS, PDHA1, and SLC31A1 had a bad prognosis." (PMID 36059516, 2022). "Unlike lung or kidney cancers, SLC31A1 expression was upregulated in breast cancer samples compared with normal tissues, and predicted poor prognosis." (PMID 35996075, 2022). "The results indicated that high SLC31A1 expression in breast cancer predicted better response to paclitaxel, but not doxorubicin or docetaxel." (PMID 35996075, 2022). "Additionally, patients with aggressive breast cancer subtypes: TNBC and HER2+ had higher SLC31A1 expression than luminal type A or B subtypes." (PMID 34911956, 2021). "In the present study, SLC31A1 expression was significantly decreased in non-response groups with respect to response groups, when breast cancer patients were treated with conventional chemotherapy regimens including FEC plus docetaxel, TA, and FEC plus paclitaxel." (PMID 37884650, 2023).
breast cancer (continued). "Moreover, AUC was 0.854, 0.746, and 0.729 in the corresponding chemotherapy regimens, revealing that SLC31A1 was able to distinguish non-response groups from response groups in breast cancer." (PMID 37884650, 2023). "In addition, SLC31A1 was positively related to the expressions of immune checkpoints CD274 and CTLA4, suggesting that targeting SLC31A1 might be a potential way to improve immunotherapy efficacy in breast cancer." (PMID 37884650, 2023). "Only SLC31A1, but not CDKN2A, was negatively related to a favorable overall survival in breast cancer." (PMID 37884650, 2023). "However, there is no report on SLC31A1 and CAF in breast cancer." (PMID 37275369, 2023).
ovarian carcinoma (21 papers, 2012 to 2024). A malignant neoplasm originating from the surface ovarian epithelium. "The expression of SLC31A1 is associated with a variety of cancers, including lung cancer, pancreatic cancer, and ovarian cancer." (PMID 37091865, 2023). "Among these five CRRs, SLC31A1 was associated with chemoresistance to platinum in osteosarcoma, lung cancer, and ovarian cancer." (PMID 36226193, 2022). "Consistently, low levels of SLC31A1 mRNA are also associated with poor clinical response to platinum-based therapy in ovarian cancer patients." (PMID 29844858, 2018). "SLC31A1 has been confirmed to be associated with various diseases such as lung cancer, ovarian cancer, and pancreatic cancer, but it has not been studied in GC." (PMID 36249422, 2022). "Among these dysregulated genes, for example, COX17 plays vital role in the development of TNBC, while SLC31A1 is a key target gene for chemoresistance in ovarian cancer, indicating cuproptosis related genes might also play vital roles in BLCA." (PMID 36211344, 2022). "IHC staining data from 50 clinical samples in our hospital indicated that both of the expression scores of SLC31A1 and GTSE1 in ovarian malignant tumors were significantly higher than those in normal ovarian tissues (all p < 0.0001), they were positively correlated (R = 0.53, P < 0.001)." (PMID 36307842, 2022).
lung carcinoma (18 papers, 2014 to 2025). "Lung cancer risk was shown to be elevated by the minor alleles of SLC31A1-rs10981694 and FDX1-rs10488764." (PMID 36454396, 2022). "The clinically relevant and biologically functional SLC31A1 polymorphism provides potential biomarker for outcome prediction of platinum-based chemotherapy and lung cancer management." (PMID 29844858, 2018). "An additional study observed increased platinum resistance in lung cancer patients that was associated with two SLC31A1 variants (rs7851395 and rs12686377)." (PMID 28640195, 2017). "By fostering accumulation of intracellular free copper, SLC31A1 was considered as a key molecule promoting cuproptosis in kidney and lung cancer cell lines." (PMID 35996075, 2022). "Increased SLC31A1 expression, in combination with platinum-based chemotherapy, correlates with increased survival in ovarian and lung cancer." (PMID 35681748, 2022). "Recent studies have indicated that SLC31A1 may play a role in colorectal and lung cancer tumorigenesis." (PMID 36973786, 2023). "Researchers also found that the microsatellites of SLC31A1 and ATP7B were associated with lung cancer risk, suggesting that the expression levels of copper homeostasis-related genes may also influence the process of lung cancer development." (PMID 36882769, 2023). "Because SLC31A1 is ubiquitously expressed in all tissues of vertebrates, part of administered platinum agents could be imported into all tissue cells including lung cancer cells as target, the other fraction remains bound with plasma protein in circulation." (PMID 29844858, 2018). "Furthermore, the C allele, which was associated with poor outcomes of platinum-based therapy in NSCLC patients, correlated with reductions in luciferase activity in reporter assay and in SLC31A1 transcript expression in clinical lung cancer tissues as well." (PMID 29844858, 2018). "However, the resectable cases only account for 10-15% of diagnosed NSCLC patients, and routine measure of SLC31A1 mRNA or protein expression in lung cancer tissues is not convenient." (PMID 29844858, 2018).
glioma (14 papers, 2022 to 2025). A benign or malignant brain and spinal cord tumor that arises from glial cells (astrocytes, oligodendrocytes, ependymal cells). "Although SLC31A1 is involved in copper metabolism and is significantly associated with the prognosis and biological behavior of gliomas, the authors point out that its exact role in cuproptosis is still unclear and requires further investigation." (PMID 39062119, 2024). "As for survival analysis, the high expression of FDX1 and SLC31A1 protein was associated with poor survival in glioma patients (p < 0.05 for FDX1 and p < 0.001 for SLC31A1)." (PMID 36856182, 2023). "In patients with tumor types including adrenocortical carcinoma, low-grade glioma, or mesothelioma, higher SLC31A1 expression was associated with shorter overall survival and disease-free survival." (PMID 36973786, 2023). "Then, a receiver operating characteristic (ROC) curve was constructed to examine the diagnostic significance of SLC31A1 expression by comparing SLC31A1 expression in normal tissue specimens (data obtained from GTEx) and glioma tissues (from the TCGA database)." (PMID 37610668, 2023). "In this part, we found that the SLC31A1 is an independent risk factor of glioma patients, which is useful for the outcome prediction of glioma." (PMID 37610668, 2023). "According to our results, the expression of most immune cell markers for various types of M1/M2 macrophages, TAMs, DCs, and T cells is linked to the SLC31A1 gene expression level in glioma." (PMID 37610668, 2023). "All of the results indicate that the SLC31A1 gene is associated with glioma." (PMID 37610668, 2023). "Laboratory investigations have demonstrated that SLC31A1 enhances glioma cell proliferation and migratory capabilities." (PMID 41216190, 2025). "We found that the SLC31A1 gene expression is significantly upregulated (p < 0.0001) in glioma cell lines." (PMID 37610668, 2023). "As we investigated, the SLC31A1 gene expression positively correlates with Th2 cells, which indicated that the SLC31A1 has a strong impact on the TME of glioma." (PMID 37610668, 2023). "Since the HR values of FDX1, SUMF1, SLC31A1 were the highest in the seven‐gene signature, we were going to validate their protein expression in human glioma specimens." (PMID 36856182, 2023). "In our research, we also explored the relationship between SLC31A1 gene expression and the outcomes of glioma patients." (PMID 37610668, 2023). "Our results indicate that the SLC31A1 gene expression can promote the formation of an immune-suppressive glioma microenvironment." (PMID 37610668, 2023). "The in vitro knockdown experiment also shows that the SLC31A1 KD strongly impaired the proliferation and migration of glioma cells, which is the same as we analyzed by the in silico data." (PMID 37610668, 2023). "The glioma patients have higher SLC31A1 expression levels, which increase as the World Health Organization (WHO) grade escalates." (PMID 37610668, 2023). "We downloaded the SLC31A1 protein expression data and analyzed the expression difference between normal brain tissue and glioma." (PMID 37610668, 2023). "We then explored the relationship between SLC31A1 gene expression and 24 distinct immune subtypes in glioma using the online analysis tool of the TIMER2.0 database." (PMID 37610668, 2023). "In vitro study shows that SLC31A1 can promote cell proliferation, and migration, and depress the cell apoptosis of glioma cells." (PMID 37610668, 2023). "Following that, we further investigated the possible mechanism of how the SLC31A1 gene expression influences glioma progression." (PMID 37610668, 2023). "As demonstrated, the SLC31A1 gene expression at the mRNA level is upmodulated in glioma patients (p < 0.001)." (PMID 37610668, 2023). "Then, we tested the SLC31A1 gene expression difference between glioma cell lines U87, LN229, U251, U343, and the average human fetal glial cell line SVGp12 using a Real-time Quantitative PCR Detecting System." (PMID 37610668, 2023).